MIR1204 (microRNA 1204)
Synonyms: hsa-mir-1204
Gene: MicroRNA gene on chromosome 8 (127,795,962 to 127,796,028, forward strand). Ensembl gene ENSG00000283710.
Homologues: Orthologues: macaque MIR1204 (100% identical).
Diseases named in the same sentence as MIR1204 in open-access papers:
MIR1204 is named in the same sentence as 2 diseases in open-access papers, as found by Europe PMC text mining. Sharing a sentence is not in itself a finding about the gene and the disease. The quoted sentences say what the papers report.
cancer (2 papers, 2013 to 2025). A tumor composed of atypical neoplastic, often pleomorphic cells that invade other tissues. "Compared to RWPE-1, cancer cells showed stronger H3K27ac signals, and MIR1204, IER2, SMAD3, and FOXA1 were SE-associated in PC-3 and DU145 but not RWPE-1." (PMID 41330917, 2025). "Co-amplification of PVT1 and MIR1204 with MYC has been reported in several types of cancers, and their oncogenic roles have been also suggested." (PMID 23716474, 2013).
tumor (1 paper, 2021). "The MIR1204 gene was the most hypomethylated in tumor samples when compared with corresponding normal resected tissues (−2.9-fold methylation difference)." (PMID 34885060, 2021).